LINC00462 (long independently transcribed non-coding RNA 462)
Gene: Long non-coding RNA gene on chromosome 13 (48,576,969 to 48,590,598, reverse strand). Ensembl gene ENSG00000233610.
Diseases named in the same sentence as LINC00462 in open-access papers:
LINC00462 is named in the same sentence as 5 diseases in open-access papers, as found by Europe PMC text mining. Sharing a sentence is not in itself a finding about the gene and the disease. The quoted sentences say what the papers report.
pancreatic cancer (7 papers, 2018 to 2022). "The upregulation of LINC00462 was found to be associated with larger tumor size, poorer tumor differentiation, TNM stage, and metastasis of pancreatic cancer patients." (PMID 33520012, 2020). "Moreover, LINC00462 up-regulation increases the migration and invasiveness of pancreatic cancer cells through enhancement of epithelial-mesenchymal transition (EMT) and accelerated growth and metastasis of pancreatic cancer in vivo." (PMID 34827663, 2021). "In addition, linc00462 promotes the invasiveness of pancreatic cancer cells via regulating the miR-665/TGFBR1-TGFBR2/SMAD2/3 pathway, hence it could promote cell progression." (PMID 35310430, 2022). "The overexpression of LINC00462 improved TGFBR1 and TGFBR2 expression levels to activate the SMAD2/3 signaling pathway in pancreatic cancer." (PMID 33622186, 2021). "We also identified that the low expression of MEG3, LINC01963, and LINC00261 and the high expression of MACC1-AS1, LINC00462, LINC01559, and UCA1 were significantly correlated with worse survival in pancreatic cancer patients." (PMID 34827663, 2021). "LINC00462 participates in the miR-666/TGFBR1-TGFBR2/SMAD2/3 or AKT signaling pathways to promote tumor invasion and progression in pancreatic cancer and hepatic cancer." (PMID 34238114, 2021). "The expression level of linc00462 was significantly higher in tumor tissues, which is correlated with large tumor size, poor tumor differentiation, TNM stage and distant metastasis in patients with pancreatic cancer." (PMID 29899418, 2018).
tumor (4 papers, 2018 to 2022). "Moreover, we demonstrated that linc00462 plays an oncogenic role in PC by promoting tumor growth and metastasis using the vivo animal model." (PMID 29899418, 2018). "However, the molecular mechanisms by which linc00462 promote cell proliferation, cell migration, cell invasion and tumor metastasis remain unclear." (PMID 29899418, 2018).
cancer (2 papers, 2020 to 2021). A tumor composed of atypical neoplastic, often pleomorphic cells that invade other tissues. "In addition, LINC00462 can promote the cancer cell migration and the invasion by promoting the epithelial-mesenchymal transition." (PMID 33381151, 2020).
LINC00462 also shares sentences with these, for which no sentence is quoted: breast carcinoma (2 papers); hepatic cancer (1).